IL6 (interleukin 6)
Diseases named in the same sentence as IL6 in open-access papers (continued):
Sharing a sentence is not in itself a finding about the gene and the disease.
tumor (continued). "In addition, the expression of other pro-inflammatory cytokines, such as IL-1, IL-6, or IL-22, produced during the tumor-induced inflammatory response, are also likely to be integrated in this network." (PMID 30559930, 2018). "Furthermore, we found a significant increase in the immature MDSC subset with the CD11b+Gr-1−F4/80−MHC-II− phenotype in the primary tumors of the 4T1WT mice, which were regulated by tumor-derived IL-6." (PMID 30083161, 2018). "Cancer-associated adipocytes have been associated with enhanced production of matrix metalloproteinase-11 (MMP-11) and pro-inflammatory cytokines (IL-1β and IL-6), as well as increased degradation of lipids, to provide additional energy to malignant cells at the tumour front." (PMID 30261606, 2018). "We next performed IHC and IF analysis for ERβ and IL6 on these tumor masses." (PMID 29970138, 2018). "One study showed that ERα-positive, but not ERα-negative, cell lines displayed enhanced growth in response to IL-6 in vitro, and in vivo, MCF-7 cells engineered to express ectopic human IL-6 displayed significantly greater tumor growth in athymic nude mice when compared to parental MCF-7 cells." (PMID 29601539, 2018). "Other OSM-related factors, such as IL-6 and IL-8, may promote CTCs by increasing tumor cell invasion, detachment, and EMT." (PMID 29898744, 2018). "Finally, the overexpression of RANTES and IL-6 in MCF-7 cells significantly increased the in vivo tumor growth." (PMID 29707128, 2018). "Other parameters with a large influence on the tumor volume are the death rate of the terminally differentiated cancer cells, δD; the minimum probability of CSC self-renewal, PSmin*; the production rate of IL-6 by tumor cells, ρ; and the total number of IL-6 receptors on CSCS, RTS." (PMID 29351275, 2018). "By acting on endothelin-1 (ET-1) receptor, tumor-derived ET-1 induced the migration of both tumor cells and macrophages into lungs and also induced the expression of pro-inflammatory cytokines including IL-6 and CCL2 in several bladder cancer lung metastasis models." (PMID 30597969, 2018). "The effects of CM and IL-6 on cell viability imply that observed changes in cell viability are not caused by the acquisition of a mesenchymal phenotype (EMT), but rather an additional effect of EMC in the tumor microenvironment." (PMID 29423072, 2018). "We found that IL-6 knockdown strikingly inhibited tumor growth (P < 0.001, P < 0.001)." (PMID 30083161, 2018). "Indeed, once in contact with tumour cells, BM‐MSCs trans‐differentiate into CAFs, strongly increasing GRO‐α, MCP‐1, IL‐6 and IL‐8 levels in the tumour microenvironment." (PMID 29517849, 2018). "While a variable capacity to secrete IL-6, IL-1β and TNF-α is shared by differentially polarized macrophages, an IL-12 low/IL-10 high phenotype is the hallmark of M2 macrophages, which are known to promote tumor growth." (PMID 29454317, 2018). "CAFs were reported to be the major source of IL-6 in the tumor microenvironment of ovarian tumors." (PMID 30380628, 2018). "In addition to the induction of antitumor immune response, the cancer immunotherapy functions through the alteration of tumor microenvironment by the release of pro-inflammatory cytokines such as IL-12, IL-6, and TNF-α." (PMID 30081891, 2018). "Importantly, a pharmacodynamic biomarker of tumor rejection was identified by coordinated elevations in serum IFNγ, IL-2, IL-4, IL-5, IL-6 and IL-17A." (PMID 30400822, 2018). "IL-6 is part of a complex mixture of cytokines and chemokines in the tumor microenvironment." (PMID 30038723, 2018). "Additionally, IL-6 production by tumor cells leads to STAT3 pathway activation in head and neck squamous cell carcinoma." (PMID 30487436, 2018). "IL-6 is one of the major cytokines present in the tumour microenvironment." (PMID 30310111, 2018). "In the generation of tumor cells, angiogenesis, and inflammation, IL-6 is active." (PMID 29963457, 2018).
tumor (continued). "However, the simultaneous overexpression of RANTES and IL-6 in MCF-7 cells produced a more significant increase in tumor growth in vivo confirming that these factors cooperate to induce a more aggressive phenotype." (PMID 29707128, 2018). "Interestingly, interleukin-6 (IL-6) has been shown to decrease tumor growth in LNCaP xenograft models." (PMID 29854771, 2018). "IL6 levels not only increased in patients but also in the tumor." (PMID 30326660, 2018). "Interleukin-6 (IL-6) is an important trigger for the expansion and recruitment of myeloid-derived suppressor cells (MDSCs), which are regarded to be major coordinators of the immunosuppressive tumor microenvironment." (PMID 30083161, 2018). "Mechanistically, IL-33 facilitated tumor development in vivo through the up regulation of IL-6." (PMID 30205617, 2018). "Hence, the use of IL-6-independent tumor cells is necessary to clarify the immunosuppressive role of TAM-like cells in vivo." (PMID 29456539, 2018). "In addition, a xenograft mouse model was used to observe differences in ERβ subtype tumor growth with respect to IL6 expression." (PMID 29970138, 2018). "Indeed, eosinophils were induced to produce TNF-α, IL-6 and likely others tumor-promoting cytokines upon stimulation with IL-17." (PMID 30510245, 2018). "Additionally, IL-6 has been shown to target cell cycle progression and anti-apoptotic genes leading to tumour proliferation and anti-apoptotic potential." (PMID 29631586, 2018). "To determine whether IL-6 promoted tumor growth and metastasis by directly affecting the biological behavior of 4T1 cells, we examined the effects of IL-6 knockdown on the proliferation, apoptosis, migration, and invasion of 4T1 cells in vitro." (PMID 30083161, 2018). "Blunting of IL-6 signaling in macrophages reduces tumor development in the CAC mouse model." (PMID 30591653, 2018). "IL-6 in a tumor microenvironment is reported to promote cancer cell migration." (PMID 29921758, 2018). "Additionally, the presence of IL-6 within the tumor microenvironment can promote dendritic cell to macrophage differentiation, thus suppressing the activation of the anti-tumor adaptive immune response." (PMID 29805773, 2018). "In this regard both, IL-6 and 8 have been shown to have important roles in maintaining oncogenic signaling in cancer cells, in promoting cancer stem cell maintenance and in the regulation of the tumor microenvironment." (PMID 30622432, 2018). "But the proliferation of T cells in 4T1IL-6low tumors was recovered compared with that in 4T1NC tumors (18.30 ± 1.91 vs. 11.03 ± 0.73, P = 0.0236), which implied that IL-6 reduction in tumor microenvironment can relieve immunosuppression on T cell proliferation and function." (PMID 30083161, 2018). "Our model allows for the quantification of the temporal changes fractional occupancies of bound IL-6 receptors and their impact on tumor growth dynamics, which is precisely the level of detail required to better understand targeted therapies that antagonize IL-6 signaling." (PMID 29351275, 2018). "While this finding needs further evaluation, it might be that IL-6/leptin-induced STAT3 is required earlier in DEN-induced HCC e.g. in tumor initiation or during progression." (PMID 30224299, 2018). "Second, IL6 is released, inducing the activation of neutrophils within the tumor microenvironment." (PMID 29556041, 2018). "Activation of IL6–JAK–STAT3 axis by pUS28 could be one of the mechanisms involved in tumor development." (PMID 30081496, 2018). "We found that continuous IL-6 significantly facilitated the cell proliferation, clone formation potential and tumor growth in vivo." (PMID 30482241, 2018). "The Let7 family of microRNAs can controls Il6 expression in tumor and inflammatory cells." (PMID 30568188, 2018).
tumor (continued). "Consistent with the critical role of endothelial IL-6 in mouse survival, EC-specific knockout of IL-6 significantly reduced tumor growth, as indicated by a 70% decrease in average tumor volume (at day 12 after tumor implantation)." (PMID 29422647, 2018). "IL6 signaling and tumor cell growth was blocked with IL6 neutralizing antibodies." (PMID 30087267, 2018). "Additionally, PERK-mediated upregulation of vascular endothelial growth factor (VEGF), fibroblast growth factor 2 (FGF2), and interleukin-6 (IL-6), and downregulation of anti-angiogenic cytokines remarkably facilitate tumor growth." (PMID 30282948, 2018). "BMA-derived IL-6 plays an indispensable role in tumor metastasis." (PMID 30013512, 2018). "Moreover, increased expression of iNOS, NOX2, and IL-6 in MDSCs is critical for them to exert tumor promoting functions." (PMID 30405034, 2018). "Therefore, the fractional occupancies of bound receptors can be a useful tool for quantifying the influence of tumor cell-secreted IL-6 on the tumorigenic potential of CSCs and subsequently on tumor growth dynamics." (PMID 29351275, 2018). "Above results showed that CD11b+Gr-1− MDSCs transfer could reverse IL-6-knockwown mediated tumor growth suppression." (PMID 30083161, 2018). "Like VEGF, IL-6 facilitates tumor vascularization and promotes tumor growth." (PMID 29389898, 2018). "Hypoxia has been shown to induce the production of stromal cell-derived factor 1α (SDF1α) by hypoxic tumor cells, which binds to C-X-C chemokine receptor type, IL-8, and IL-6, and directly regulates the function and differentiation of MDSCs within the tumor microenvironment." (PMID 30061885, 2018). "The produced CCL2 recruited CD11b+Ly6Chigh inflammatory monocytes to the lungs, where the recruited cells matured into CD11b+Ly6C− IM-like macrophages which produced IL-6 and triggered fibrin deposition, thereby providing the tumor cells with signals to support their survival and growth." (PMID 30597969, 2018). "In addition, tumor cell lysates generate interleukin (IL) 1α/β, IL-6, IL-8, and TNF-α secretion from immune cells, and especially IL-1 and IL-6 play an important role in inflammatory regulation process." (PMID 30680248, 2018). "The tumor IL-6 is then secreted and generates its positive feedback in an autocrine fashion." (PMID 30134795, 2018). "It is possible that overexpression of Src in the cells could dramatically stimulate the production of IL-6, suggesting a critical role for the oncogene in manipulating the tumor microenvironment." (PMID 29707119, 2018). "Above data implied that tumor-derived IL-6 predominantly triggered SOCS3 suppression in e-MDSCs, and hence it could be reversed by using the IL-6R blocking antibody." (PMID 30083161, 2018). "To further explore whether ectopic expression of IL6 stimulated by E2 affects tumor growth in vivo, we established a urethane-induced adenocarcinoma model." (PMID 29970138, 2018). "Increased IL-1 and IL-6 and might play an indirect role in potentiating anti- tumor immunity in vitro." (PMID 30410443, 2018). "On the other hand, other reports indicate that the activation of NF-κB is also required for tumor development in many cancer models, due to the release of proinflammatory cytokines such as TNF-α and IL-6, which can trigger prosurvival signals for tumor cells supporting their growth and progression." (PMID 28660349, 2018). "Furthermore, BMMSCs derived from patients with MM were found to deliver the cytokine IL-6, which is known to promote tumor formation and progression." (PMID 29724992, 2018). "Apart from their putative role promoting tumor growth, both angiotensins could also be responsible of the proinflammatory status found here, with increased levels of IL-6 and TNF-α, acting through their angiotensin receptors." (PMID 29373553, 2018). "Additionally, local tumor cell density regulates cell density-dependent phenotypes through the synergistic signaling of IL-6 and IL-8 via the JAK2/STAT3 pathway." (PMID 30220965, 2018).
tumor (continued). "IL-6 is critical for tumor microenvironment regulation and may be a key regulator during colorectal tumorigenesis via regulation of tumor-promoting inflammation." (PMID 29546074, 2018). "During the tumor invasiveness, IL-6 levels released by microglia increase MMP-9 levels." (PMID 30123112, 2018). "IL-6 specifically assists in tumor cell survival and growth." (PMID 29696001, 2018). "Inactivation of IL-6 or the IL-6Rα in mice reduces tumor formation in the CAC mouse model." (PMID 30591653, 2018). "Subsequently, functional studies revealed that autocrine production of IL-6 by tumor cells confers resistance to several chemotherapeutic agents, suggesting that acquisition of the ability of tumor cells to produce IL-6 represents another self-protective mechanism." (PMID 29946544, 2018). "Parameter values obtained using IL-6+/+ data for primary tumor cells." (PMID 29351275, 2018). "Overall, microglial cells are not the only glial cells that release IL-6, astrocytes too expressed high amounts of IL-6, in particular when co-cultured with GB cell lines, contributing to tumor migration and invasion through the release of the active form of MMP-14 by GB cells." (PMID 30123112, 2018). "Several studies using immunoassays in colorectal tissue and in vitro cultures demonstrate that Fn infection increases the expression of inflammatory cytokines in tumor tissue, including IL-6, IL-8, TNF-α, and Cox-2, and these cytokines are capable of promoting tumor development." (PMID 30544946, 2018). "On the other hand, IL-6 apparently plays a prominent role in inflammatory and neoplastic diseases." (PMID 29666579, 2018). "IL-6 and other inflammatory factors have doubtless pro-tumor effects." (PMID 30013512, 2018). "Importantly, IL-6 plays key role in promoting tumor progression and immunosuppression, mainly through the downstream activation of JAK/STAT3 signaling." (PMID 29541413, 2018). "Furthermore, this pre-metastatic niche provides a platform of chemokines (IL1, IL6 and TNFα), growth factors and adhesion molecules, enabling circulating tumour cells to engraft the secondary site." (PMID 30577495, 2018). "Hence, high IL-6 levels promote an anti-apoptotic, proliferative state in tumor cells, thereby enabling the tumor cells to become anti-cancer drug resistant to both chemotherapy and cancer immunotherapy." (PMID 30038723, 2018). "In this case, IL-6 and IL-8 signaling can lead to tumor initiation, progression, and metastasis." (PMID 29868482, 2018). "Considering the abundant immune cells and inflammatory factors in the bone marrow microenvironment, BMAs may also have the potential to release a significant amount of sIL6R and bind with IL6 to activate the trans-signaling in tumor cells." (PMID 30013512, 2018). "Consistent with the previous report, our observations support the idea that tumour‐induced IL6 may modulate hepatic function." (PMID 29540470, 2018). "Tumor weight and plasma IL-6 levels were significantly lower in KF mice than in TB mice." (PMID 29443873, 2018). "IL-6/STAT3 is the main pathway through which IL-6 regulates tumor-promoting activities." (PMID 29930760, 2018). "KJS018A also restrained tumor growth and levels of IL-6 and Cox-2 in immunohistochemistry staining." (PMID 30154906, 2018). "Values for the IL-6 secretion rate by tumor cells, ρ, vary quite widely in the literature." (PMID 29351275, 2018). "This supports the idea that an IL-6 antagonist could temper the effects of IL-6-induced pathways, thereby impeding tumor growth." (PMID 29351275, 2018). "Thus, we postulate that the exo-adipocytes in our study are a kind of CAA as they exhibit tumor-promoting capacity and higher expression of pro-inflammatory factors such as IL-6, IL-8, and MCP-1 whose higher expression in CAA has been reported." (PMID 29898759, 2018).
tumor (continued). "Thus, HBXIP/HOXB13 axis efficiently circumvents TAM by converting ER-α-dependent cell growth to IL-6-dependent, providing alternative proliferative stimuli for tumor cells and making the cells continue to grow." (PMID 29471853, 2018). "Dioscorea japonica feeding and Dioscorea japonica extract topical application suppressed the expression of cyclooxygenase-2, microsomal prostaglandin E synthase-1, interleukin-1β and interleukin-6 and inhibited tumor formation, hyperplasia and inflammatory cell infiltration." (PMID 29610553, 2018). "We next used western blot to measure the expression of ERβ and IL6 in mouse tumor tissue." (PMID 29970138, 2018). "Thus, the evidence suggested that the suppression of tumor metastasis by antrodan was related to the modulation of the IL-6/STAT-3 pathway." (PMID 29794990, 2018). "To clarify whether IL-6 promotes WAT lipolysis and browning in cancer cachexia, we used anti-IL-6 receptor antibody to inhibit IL-6 in Colon 26 tumor-bearing cachectic mice." (PMID 29338749, 2018). "Furthermore, we found positive correlation between the level of tumor-derived interleukin-6 (IL-6) and the recruitment of e-MDSCs locally." (PMID 30083161, 2018). "Moreover, Il6−/− mice exhibited elevated apoptosis and decreased proliferation in tumor specimens with lower cyclin D expression and Ki-67 positive rate." (PMID 30498394, 2018). "Interestingly, IL-6 has been shown to play both pro- and anti-apoptotic roles depending on tumor type." (PMID 30671025, 2018). "IL-6 has been shown to exhibit both pro- and anti-tumor activities." (PMID 30348199, 2018). "STAT3 is constitutively activated in both tumor and immune cells by IL-6." (PMID 29419779, 2018). "Both authors argue that high serum IL-6 levels may be useful in distinguishing between different neoplasms and between benignity and malignancy." (PMID 30038723, 2018). "To examine whether IL-6 affects tumor cell proliferation and apoptosis, we established stable transfectants with shIL-6 expression in PANC-1 cells." (PMID 29693005, 2018). "Knockdown tumor-derived IL-6 increased the percentage of mature myeloid cells significantly." (PMID 30083161, 2018). "Importantly, soluble factors mediating drug resistance such as IL-6 can be released by the tumor cell itself or the TME." (PMID 29946544, 2018). "IL-6/STAT3 signaling cascade induces many downstream targets and its dysregulation could contribute to initiation, promotion, and progression of tumor-associated inflammation." (PMID 29385191, 2018). "Thus, JAK1 mediated anti-proliferative signaling of IL-6; implying that the strong silencing of JAK1 expression in parental LNCaP cells possibly contributed to their thriving in an inflammatory, IL-6-rich tumor micro-environment." (PMID 29441069, 2018). "Curcumin reduced intratumoral IL-6 production and metastasis formation in a breast cancer model and, when combined with cryoablation, induced robust anti-tumor T cell immunity and reduced tumor growth." (PMID 30687714, 2018). "Adipocytes within the tumor microenvironment secrete leptin and IL-6." (PMID 30515368, 2018). "The IL-6/STAT3 pathway has been proved to be a crucial tumor promoter in CAC." (PMID 30498394, 2018). "Furthermore mix leukocyte culture obtained from CD200fc-treated tumor-bearing mice secreted markedly lower levels of IL-6." (PMID 29721190, 2018). "Increase in circulating IL6 can be a consequence of tumour‐induced inflammation." (PMID 29540470, 2018). "As IL-6 was a regulator of the FAP+ HO-1+ TAM phenotype in this model, we analysed pulmonary metastasis in 4T1 tumours grown in Il6−/− mice, and in agreement, found significantly fewer metastases in the absence of host-derived IL-6, demonstrating that IL-6 played a key role in the process." (PMID 30054470, 2018). "Here we show that loss of IL-6 reduced JAK-STAT signalling, tumour incidence and metastasis." (PMID 29343721, 2018).